BCL2 (BCL2 apoptosis regulator)
Diseases named in the same sentence as BCL2 in open-access papers (continued):
Sharing a sentence is not in itself a finding about the gene and the disease.
lymphoma (continued). "In 2006, TW-37 was developed as a small molecule inhibitor of Bcl-2, Bcl-XL, and Mcl-1 and was shown to have anti-cancer activity in lymphoma cells." (PMID 32257914, 2019). "Bcl-2 is very highly expressed in human FL, and previous work has shown that lines of mice expressing higher amounts of Bcl-2 in B cells than the BCL2-tg line have a higher propensity to form lymphomas." (PMID 31204070, 2019). "The remaining 19 MYC rearranged patients, lacking an additional BCL2 or BCL6 translocation, were defined single hit lymphomas (SHL – MYC+/BCL2-/BCL6-)." (PMID 31976479, 2019). "Our analysis provided a novel look on the transition range between FL and DLBCL, on DLBCL with poor prognosis showing expression patterns resembling that of Burkitt’s lymphoma and particularly on ‘double-hit’ MYC and BCL2 transformed lymphomas." (PMID 31039827, 2019). "Venetoclax (ABT-199/GDC-0199) is a highly selective bioavailable inhibitor of BCL-2 protein, which is more effective and less valid against BCL-xL in BCL2-dependent leukemia and lymphoma cell." (PMID 31293422, 2019). "We examined the in vitro antiproliferative activity of BCL2-selective inhibitors in a wide range of lymphoma cell lines, including DLBCL, mantle cell lymphoma (MCL), Hodgkin lymphoma (HL), Burkitt lymphoma (BL), and anaplastic large cell lymphoma." (PMID 30404918, 2018). "Double-hit (DH) lymphomas, defined as lymphomas with MYC translocation combined with BCL-2 or BCL6 translocation, are among the most aggressive variants." (PMID 30287880, 2018). "High expression of Bcl-2 correlated with poor clinical response to therapy in some of the hematologic malignancies, mainly lymphomas, CLL and AML." (PMID 29515335, 2018). "This is in line with other group's finding that CFZ sensitizes rituximab-resistant lymphoma cells to chemotherapy but upregulates Bcl-2 expression, which implies a complex modulation among these mitochondria-associated proteins to decide cell fate." (PMID 29867453, 2018). "Overexpression of the pro-survival member BCL-2 is a well-established mechanism contributing to oncogenesis and chemoresistance in several cancers, including lymphoma and leukemia." (PMID 29732004, 2018). "The role of the combination of lenalidomide with standard R-CHOP21 in other subgroups of DLBCL with worse prognosis, such as MYC/BCL2 double expressors or double hit lymphomas remains to be defined, and further studies are ongoing." (PMID 30410035, 2018). "Remarkably, higher BCL-2 levels within lymphoma cells were shown to correlate with an increased sensitivity to venetoclax treatment." (PMID 29899864, 2018). "To assess selectivity in a cellular context, we tested (Ra)-7 in Eμ-Myc lymphoma cell lines stably expressing the prosurvival Bcl-2 proteins Mcl-1, Bcl-2, Bcl-xL, Bfl-1/A1, or Bcl-w." (PMID 30559424, 2018). "Our data provide a mechanistic rationale for combination strategies to disrupt lymphoma cell codependency on BCL2 and MCL1 proteins in DLBCL." (PMID 30404918, 2018). "Synergy with duvelisib was prominent in lymphoma lines with approved and emerging drugs used to treat HM, including dexamethasone, ibrutinib, and the BCL-2 inhibitor venetoclax." (PMID 30067771, 2018). "Previous study indicated that some lymphoma is highly aggressive when it expressed C-MYC gene accompanied by expression of BCL-2 or BCL-6 genes." (PMID 30666200, 2018). "Among those with the worst outcomes are patients with “double hit” lymphomas (DHL), defined by the presence of a c-MYC mutation in conjunction with the B cell leukemia-2 (BCL-2) translocation." (PMID 29765528, 2018). "DLBCLs that co-express high levels of MYC and BCL-2 proteins due to mechanisms other than chromosomal translocations are referred to as “dual expresser lymphomas” (DEL) and represent ~30% of DLBCL." (PMID 30671383, 2018). "There were high expectations of clinical benefit with venetoclax in low grade lymphomas, which historically have served as the canonical disease model for BCL-2 overexpression." (PMID 30671383, 2018).
lymphoma (continued). "Pharmacologic induction of NOXA, using the histone deacetylase inhibitor panobinostat, decreased MCL1 protein abundance and increased lymphoma cell vulnerability to BCL2 inhibitors in vitro and in vivo." (PMID 30404918, 2018). "BCL-2 protein accelerates the growth of lymphoma and promotes the resistance of tumor cells to chemical drugs." (PMID 30666200, 2018). "DLBCL lymphomas that contain both rearrangements in BCL-2 and translocation of MYC are classified as “double hit lymphomas” (DHL) and represent ~10% of DLBCL cases." (PMID 30671383, 2018). "Additional deregulations were then described such as 1q amplification leading to Mcl-1 overexpression in MM, Bim deletion in lymphoma cell lines or miRNA deregulation leading to Bcl-2 overexpression in CLL." (PMID 30666297, 2018). "In contrast, single-agent BCL2 inhibitor is sufficient to induce cell death in lymphoma cells harboring NOXA amplification." (PMID 30404918, 2018). "In conclusion, our findings provide insights on the mechanism of action of S55746 and provide a mechanistic rational for combining panobinostat with BCL2 inhibitors for the treatment of lymphoma." (PMID 30404918, 2018). "Overexpression of Bcl-2 in human breast epithelial cells and mouse lymphoma cells increases [Ca2+]ER44,45." (PMID 29531834, 2018). "BIM has been suggested to play a key role in the mechanism of synergy between BET inhibition and BCL2 inhibition in primary double-hit lymphoma cells, and SCLC." (PMID 30018745, 2018). "Recent clinical studies showed that survival of chronic lymphocytic leukaemia (CLL) is largely dependent on BCL2, and that loss of a single Bclx allele attenuates MYC-induced lymphoma in vivo." (PMID 30261081, 2018). "In conclusion, extensive research on inhibitors of the prosurvival Bcl‐2 members yielded a new class of anticancer agents, showing promise particularly against leukemia and lymphoma." (PMID 28804913, 2017). "High-grade lymphomas had significantly more biopsies with weak expression of Bcl-2 and strong expression of Bax, with a mean score of 0.47 ± 0.9, while low-grade lymphomas had a mean score of 2.6 ± 1.3." (PMID 29531548, 2017). "Recently, it was demonstrated that a double-hit lymphoma caused by multiple genetic aberrations, such as the MYC/8q24 locus and BCL2/18q21.3 locus can give rise to a unique subset of lymphomas." (PMID 28209136, 2017). "BCLW expression was negatively correlated with that of BCL2 in most lymphoma types, but in FL, BCLW was overexpressed as frequently as BCL2." (PMID 29225711, 2017). "Because of this fundamental role in lymphoma pathophysiology, Bcl-2 is also an attractive target for molecular therapy." (PMID 29531548, 2017). "MYC/BCL2 lymphomas were described as neoplasms with a phenotype characteristic of germinal center B cells: they express BCL6 and CD10, and lack IRF4, a regulator of BCL6." (PMID 28375188, 2017). "Indolent lymphomas (SLL and FCL) have a high BBPR and conversely aggressive lymphomas have a lower BBPR.A gradual downregulation of Bcl-2 protein occurred in the current study with a transition from low to high grade NHL." (PMID 29531548, 2017). "A notable trend in the BBPR among lymphoma subgroups was indicated in the present study; Bcl-2 expression was greatest in SLL and follicular lymphomas, low in high grade and absent in Burkitt’s lymphomas." (PMID 29531548, 2017).
lymphoma (continued). "Using Arf−/−Eμ-Myc/Bcl-2 mouse lymphoma cells, which overexpressed c-MYC and exogenous BCL-2 and were resistant to ABT-737, we found that suppression of DHX9 synergized with ABT-737 to reverse resistance." (PMID 28427210, 2017). "Many examples exist where the expression of BCL2 is elevated in human malignancies, particularly lymphomas." (PMID 28386116, 2017). "Our bioinformatics analysis identified a guanine to adenine point mutation in a patient with malignant lymphoma, which was predicted to destabilise the RNA G4 in the 5′ UTR of BCL2." (PMID 28386116, 2017). "For example, a landmark study by Strasser and colleagues using the Eμ-Myc model provided definitive evidence that MYC and BCL2 can functionally cooperate to accelerate lymphoma development." (PMID 28262675, 2017). "ALC or KET treatment for 24 h significantly down-regulated the expression of p-CREB, p-Akt, B cell lymphoma/lewkmia-2 (Bcl-2), BDNF and PKA." (PMID 28874724, 2017). "Blocking the intrinsic apoptotic pathway through genetic deletion of pro-apoptotic BCL-2 family genes or constitutive overexpression of BCL-2 pro-survival proteins can all accelerate lymphoma onset in this mouse model." (PMID 29137176, 2017). "A significant correlation was found between BBPR and the predicted biological behavior of indolent and aggressive lymphomas, indicating the important role of Bcl-2 and Bax in biological behavior of lymphomas." (PMID 29531548, 2017). "Our study therefore demonstrates a novel cooperative activity of ETV6/RUNX1 and BCL2 for glomerulonephritis and lymphoma development." (PMID 26919255, 2016). "In contrast, in another study, MYC/BCL6 (n = 13) showed significantly worse survival than MYC/BCL2 DHL (n = 20) after exclusion of triple-hit lymphoma." (PMID 26573234, 2016). "Here we illustrated an on-target oncogene switching mechanism from BCL6 to BCL2 as drivers of the lymphoma phenotype." (PMID 26657288, 2016). "Compared with Eμ-Myc;CD19-Cre control lymphomas, BCL-2 protein expression was comparable in the Eμ-Myc;CD19-Cre;Mcl-1fl/+ lymphomas or, curiously, was lower in the Eμ-Myc;CD19-Cre;Mcl-1fl/fl lymphomas that had retained their Mcl-1fl alleles." (PMID 26962682, 2016). "Myc-transformed murine lymphomas are sensitive to navitoclax only if they have elevated BCL2 levels." (PMID 27990281, 2016). "BCL-2 contributes to the genesis of lymphomas, is critical for cancer cell survival, and promotes chemo-resistance." (PMID 27283896, 2016). "A recently published comprehensive study of double-hit and triple-hit lymphomas showed that 62 % of double hit lymphomas involve BCL2 and 18 % involved BCL6, the remaining cases were triple-hit lymphomas." (PMID 26654227, 2015). "Our study of Bcl-2 expression included eight cases of lymphoma other than FL and overexpression was observed in half of them." (PMID 26482649, 2015). "Intrigued by our predictive and experimental data linking Bcl-2 overexpression to STAT3 activation, we set out to investigate the clinical relevance of this association in primary cells derived from patients with lymphomas." (PMID 26430964, 2015). "Bcl-2 results were available for 34/98 cases of our study group, 13/30 cases of lymphomas and 21/68 cases of RLP." (PMID 26482649, 2015). "Authors have reported that high expression of intracytoplasmic Bcl-2 protein and detection of clonality by determination of cytoplasmic κ/λ ratio support a lymphoma diagnosis." (PMID 26482649, 2015). "Although the latency of Myc-induced lymphoma was longer than in the more aggressive Myc/Bcl-2 B-ALL model, the results were also very striking, showing a considerably shorter time to death in mice lacking Stat5 expression." (PMID 26338970, 2015).
lymphoma (continued). "Since discovering that Bcl-2 interacts with IP3Rs to regulate IP3-mediated Ca2+ elevation in lymphoma cells, our intention has been to target this interaction for cancer treatment." (PMID 26317541, 2015). "A total of 54 (40 %) cases were positive for both MYC and BCL2, supporting a diagnosis of double-hit lymphoma, which is a quite high number compared to those of the literature." (PMID 26146524, 2015). "In hematological malignancies, including CLL and MCL, ABT-199 induces apoptosis and its activity was found to directly correlate with Bcl-2 expression in a set of lymphoma cell lines." (PMID 26110568, 2015). "More recently, MYC/BCL6 rearrangement lymphomas have been reported to be more frequently CD10 negative with IRF4/MUM1 positive, and cytogenetically less complex than MYC/BCL2 rearrangement lymphomas." (PMID 26416427, 2015). "Patients with both MYC and BCL2 CNA had similar outcomes to those with classic double hit lymphoma or protein double expression lymphoma (MYC and BCL2/BCL6 coexpression)." (PMID 26158410, 2015). "FISH analyses using BAC clones covering lymphoma breakpoints (BCL2, BCL6, BCL11A, CCND1, CCND3, IG-H/K/L, JAK2, LMO2, MYC, PAX5, REL) all tested normal, excluding rearrangements at these loci." (PMID 26599546, 2015). "Blockade of mitochondrial damage through forced overexpression of Bcl-2 abrogated the ability of I-BET762 to kill Eμ-myc lymphomas and inhibit their clonogenic ability, although cell-cycle arrest and growth inhibition were still evident." (PMID 26658189, 2015). "We performed expression analyses for STAT3pTyr705 and STAT3pSer727, total STAT3, Bcl-2pSer70), total Bcl-2 and Rac1, in lysates obtained from cells isolated from biopsies from 41 patients diagnosed with lymphomas." (PMID 26430964, 2015). "In humans Myc/Bcl-2 represent the poor prognosis “double hit” lymphomas, thus differing from the disease manifestation in mice." (PMID 26338970, 2015). "Patients with both MYC and BCL2 copy number aberration had similar outcomes to those with classic double-hit lymphoma (DHL) or protein double expression lymphoma (MYC and BCL2/BCL6 coexpression)." (PMID 26416427, 2015). "Pro-survival BCL2 proteins are often overexpressed in lymphoma which has encouraged the search for BCL2 inhibitors." (PMID 26393619, 2015). "Exposure of Eμ-myc/Bcl-2 and U2932-4RH lymphomas to ABT-263 LD50 in combination with the respective I-BET762 LD70 concentrations showed significant loss of mitochondrial membrane potential, cell viability and an increase in DNA fragmentation." (PMID 26658189, 2015). "None of these four CD5-positive cases showed presence of either C-MYC or BCL2 gene rearrangements; however, two patients fulfilled phenotypic criteria for double-hit lymphoma, expressing bcl2 or c-myc above the respective cutoff scores." (PMID 26071053, 2015). "Eμ-myc/bcl-2 lymphomas were completely resistant to I-BET762-mediated apoptosis after 48 h exposure." (PMID 26658189, 2015). "Among the 29 aggressive lymphomas of their study, high levels of Bcl-2 expression were present only in nine cases which were CD10 positive." (PMID 26482649, 2015). "To confirm this behaviour, we then applied this strategy to silence the anti-apoptotic expression of Bcl2, highly expressed in lymphoma cells." (PMID 25983658, 2015). "Lymphomas overexpressing Bcl-2 remained resistant to apoptosis following extended exposure to I-BET762." (PMID 26658189, 2015). "To evaluate the impact of BCL-2 overexpression on autophagy in human lymphoma, we first compared the autophagy status of the BCL-2+ Su-DHL4 with the BCL-2− Su-DHL8 DLBCL cell lines using Western blotting and the RT2 Profiler PCR array." (PMID 25362242, 2014). "As one of the double hit lymphoma, Burkitt lymphoma cells obtain two critical uncontrolled genes: BCL2 and MYC, which make the malignant cells survive and proliferate out of control." (PMID 24895574, 2014).
lymphoma (continued). "We recently discovered that GPR65 signaling in response to extracellular acidosis increases survival of leukemia and lymphoma cell lines by up-regulating the anti-apoptotic proteins Bcl-2 and Bcl-xL." (PMID 25984552, 2014). "Accumulating data have suggested that ATO - induced apoptosis is associated with down-regulation of Bcl-2 protein in NB4 cells and activation of Bax protein expression as well as reduction of mitochondrial membrane potential in lymphoma B-cells." (PMID 24887205, 2014). "Double-hit (DH) and triple-hit (TH) lymphomas are transformed B-cell lymphomas that are generally defined by the presence of MYC gene rearrangement together with either BCL2 and/or BCL6 gene rearrangement." (PMID 24887414, 2014). "PNT2258 demonstrates broad antitumor activity against BCL-2-driven WSU-DLCL2 lymphoma, highly resistant A375 melanoma, PC-3 prostate, and Daudi-Burkitt’s lymphoma xenografts." (PMID 24832107, 2014). "We aimed to determine autophagy status in primary FL and DLBCL samples and the BCL-2+/BCL-2− lymphoma cell lines using both autophagy PCR array and tissue microarray (TMA)." (PMID 25362242, 2014). "Many DHLs arise in patients with prior follicular lymphoma often with known BCL2 translocations, though de novo lymphomas are also known to occur." (PMID 25161781, 2014). "In this unrelated series, lymphomas with BCL2 or MYC translocations showed a minimum of 32% and 25% cells with signals indicative for rearrangements, respectively." (PMID 24733537, 2014). "Compared to MYC+/BCL2+DHL, BCL6+/MYC+DHL are less common, and most represent BCL2+/BCL6+/MYC+ triple-hit lymphomas." (PMID 24893165, 2014). "Another study showed downregulation of antiapoptotic Bcl-2 proteins under Obatoclax treatment in lymphoma cells." (PMID 25192188, 2014). "MYC rearrangements have been reported in 10–15% of systemic DLBCL, and they have been associated with a poor prognosis either alone or in combination with BCL2 rearrangements (“double-hit” lymphomas)." (PMID 25479599, 2014). "Translocations involving BCL2 on chromosome 18q21 were observed in five lymphomas by chromosome banding, one of them with an unbalanced translocation without identifiable partner." (PMID 24733537, 2014). "The modulation of BCL-2 following incubation with PNT2258 was confirmed in a SU-DHL-6 lymphoma cell line." (PMID 24832107, 2014). "Here, we reported that fluvastatin induced apoptosis in lymphoma cells by activating pro-apoptotic signals including caspase-3 and Bax and by suppressing anti-apoptotic signal, Bcl2." (PMID 24209962, 2013). "The effects of Bcl-2 on clinical course have been widely studied with quite a few lymphoma types previously." (PMID 24385807, 2013). "Such cases of "double-hit" leukemia/lymphoma with both BCL2 and MYC translocations warrant further study as they are often not identified early, are associated with a poor prognosis, and are incompletely understood in molecular terms." (PMID 23985173, 2013). "In our case, tumor cells did not express cytokeratins, vimentin but the expression of CD79a, CD20 and bcl2 protein was clearly positive, which enabled us to retain the diagnosis of lymphoma." (PMID 24319526, 2013). "We found that fluvastatin treatment enhanced the activation of pro-apoptotic members such as caspase-3 and Bax, but suppressed the activation of anti-apoptotic molecule Bcl-2 in lymphoma cells including A20 and EL4 cells." (PMID 24209962, 2013). "In our experimental condition, the expression ratio of Bax and Bcl2 was significantly increased in fluvastatin-treated lymphoma cells, indicating that the pro-apoptotic signals were enhanced and the anti-apoptotic signals were suppressed." (PMID 24209962, 2013). "This lymphoma cell line was chosen as it harbours both BCL2 and MYC gene translocations and therefore represents a good model system for the investigation of disease mechanisms in aggressive ‘double hit’ DLBCL." (PMID 23828858, 2013).